STAB2 (stabilin 2)
Diseases named in the same sentence as STAB2 in open-access papers (continued):
Sharing a sentence is not in itself a finding about the gene and the disease.
tumor (26 papers, 2012 to 2025). "For example, the lncRNA SATB2-AS1 was downregulated in colon cancer and can inhibit tumor metastasis by regulating the gene encoding STAB2 and affecting the tumor-immune microenvironment." (PMID 38485995, 2024). "Secondly, our study lacked the evidence from vitro experiments and the underlying mechanism of Stabilin-2 in regulating tumor progression in NSCLC remained poorly understood." (PMID 34227915, 2021). "In the context of cancer, HMMR and STAB2 have been implicated in tumor progression and metastasis." (PMID 40567905, 2025). "They described that loss of stabilin-2 may enhance survival by preventing endothelial-tumor cell adhesive interactions and microvascular invasion." (PMID 30695042, 2019). "Stab2 expression was decreased in tumor tissues in KIRP, LUSC, and BRCA, predicting better OS in KIRP and LUSC but worse OS in BRCA." (PMID 36059952, 2022). "In our analysis, Stab2 expression was decreased in tumor tissues in KIRP, LUSC, and BRCA, predicting better OS in KIRP and LUSC but worse OS in BRCA, which indicated that the specific role of Stab2 in different cancers needs to be further investigated." (PMID 36059952, 2022). "Stabilin-2 has been considered as a major clearance receptor for hyaluronic acid (HA) which shows a role in inhibiting the metastasis of tumor cells." (PMID 34227915, 2021). "SATB2-AS1 suppressed tumor metastasis in colorectal cancer by regulating STAB2, i.e., regulating cancer progression by affecting the tumor immune microenvironment." (PMID 34660577, 2021). "The lymph node itself highly expresses Stabilin-2 and acts as one of the entrapping receptors for metastatic tumor cells." (PMID 32429122, 2020). "And tumor metastasis can be prevented by blocking STAB2 function." (PMID 36777724, 2023). "Thereby, Stabilin-2 expression may be useful in predicting the tumor prognosis in patients with NSCLC." (PMID 34227915, 2021). "High stabilin-2 expression in NSCLC predicts poor tumor prognosis." (PMID 34227915, 2021). "A study in which the investigators injected PC3M-LN4 prostate cancer cells that are known to be rich in pericellular HA in mice, found that when Stabilin-2 was blocked with a blocking antibody prior to tumor injection, the number of lymph node metastases was dramatically reduced." (PMID 32429122, 2020). "Our study indicates that the SATB2/CBP transcriptional complex plays critical roles in maintaining GSC property to sustain GBM tumor growth, suggesting that targeting the STAB2/CBP signaling axis may significantly improve survival of GBM patients." (PMID 33124191, 2020). "Interestingly, this correlation analysis showed that mainly in the ICD clinical settings tumoural CALR levels positively correlated with the tumoural levels of phagocytosis-associated genes (especially PLA2G5, PLD1, RAB5A, VAMP7, STAB2)." (PMID 26314964, 2015). "Interestingly, stabilin 2 knockout mice showed not only elevated hyaluronan levels but also decreased tumor metastasis by inhibiting the rolling and tethering of B16 cells to lung endothelial cells." (PMID 23484014, 2013). "Thus, blocking the function of Stabilin-2 may inhibit the metastasis of tumor by improving the level of circulating HA." (PMID 34227915, 2021). "Unfortunately, loss of Stabilin-2 expression in the peri-tumorous environment was the least likely to occur of all the SEC markers tested and may be a significant factor for endothelial-tumor cell adhesion and invasion." (PMID 32429122, 2020). "STAB2, CD56, and CD99 were scattered positive in few cells in the biopsy tissue, but focal positive in myoid cells in the resected tumor." (PMID 35568949, 2022). "Pathological characteristics of organoids including H&E staining and expression of protein markers (CK20, CDX-2, STAB2, CD7, PAX8) were consistent to those of the original tumor." (PMID 35721089, 2022).
tumor (continued). "Inhibition of both layilin and Stab2 suppresses tumor metastasis in animal models, while HA binding protein 1 (HABP1) promotes motility of melanoma cells and tumor growth." (PMID 24213471, 2012). "To verify that, we selected 3 SC-matched tumor-peritumor tissue slices (covering 3 tumor types), and detected intermediate-state sub-cluster C5 marker (CPE) and two EC co-localization markers (VWF and STAB2) using RNAscope ISH." (PMID 37985711, 2023). "In addition, the immunohistochemical results showed the altered staining patterns of BCOR, bcl2, CyclinD1, TLE1, AR, SMA, CD117, STAB2, CD56, and CD99 in tumor tissues after chemotherapy." (PMID 35568949, 2022). "It is interesting to note that the organ with the highest expression of Stabilin-2 is the spleen, though it is not a site for tumor metastasis." (PMID 32429122, 2020). "Our result showed that the tumor tissue was positive in CK20, CDX-2, STAB2, and negative in CK7 and PAX8, which confirmed the appendix origin." (PMID 35721089, 2022). "Positive staining of CK20, CDX-2, STAB2, and negative staining of CK7 and PAX-8 was observed for the tumor tissue, indicating that the tumor was of gastrointestinal adenocarcinoma origin, rather than ovarian origin." (PMID 35721089, 2022).
cancer (11 papers, 2015 to 2025). A tumor composed of atypical neoplastic, often pleomorphic cells that invade other tissues. "One caveat of using HA as a tag to target chemotherapy to CD44+ cancer cells is the abundant expression of the HA receptor HARE/Stab2 in the liver, thus special attention to liver toxicity is essential in such studies." (PMID 26539408, 2015). "In order to demonstrate the direct involvement of miR-31 in the regulation of these genes in cancer cells, we tested the effect of miR-31 mimics and inhibitor on the expression of STAB2, RHOA, WAVE3 and other relative genes after transfection into MCF-7 and SUM-159 cells." (PMID 36313626, 2022). "From this point, Stabilin-2 may cooperate with GLUT1 in stimulating the progression of cancer cell under hypoxia condition since Stabilin-2 also showed a role in activating VEGF pathway." (PMID 34227915, 2021). "Stabilin-2 has been found to regulate the progression of cancer." (PMID 34227915, 2021). "Except for BAI1, CD31, and MerTK, the enhanced expression of Axl, Tyro3, Gas6, MFGE8, Stab2, Tim-4, CX3CL1, IDO1, Rac1, and PD-L1 was associated with decreased sensitivity to many drugs, which may partially explain the resistance to chemotherapy in cancers." (PMID 36059952, 2022). "Thus, Stabilin-2 may also participate in regulating the cancer progression though affecting the level of hyaluronic acid." (PMID 34227915, 2021). "It inhibits cancer cell proliferation and metastasis in HCC by directly targeting stabilin-2 (STAB2)." (PMID 37719019, 2023).
myopathies (1 paper, 2016). "Therefore, modulation of Stab2 expression may represent novel therapeutic strategies for regulating skeletal muscle mass in myopathies." (PMID 26972991, 2016).
STAB2 also shares sentences with these, for which no sentence is quoted: benign prostatic hyperplasia (1 paper); fibrosis (1); Hypertension (1); infection (1); infectious disease (1); inflammatory skin disease (1); mucoepidermoid carcinoma (1); scleroderma (1).